FOXM1 (forkhead box M1)
Diseases named in the same sentence as FOXM1 in open-access papers (continued):
Sharing a sentence is not in itself a finding about the gene and the disease.
cancer (continued). "In this contribution, I reviewed and discussed how our current knowledge on the oncogenic mechanisms of FOXM1 could be exploited for clinical use as biomarker for risk prediction, early cancer screening, molecular diagnostics/prognostics, and/or companion diagnostics for personalized cancer therapy." (PMID 23087907, 2012). "Here, we mainly review and discuss our current molecular understanding of the mechanisms through which FOXM1 in cancer cells executes these new roles, and thereby induces therapy resistance and inhibits apoptosis in a variety of human cancers." (PMID 41714589, 2026). "A large body of literature from different studies has demonstrated FOXM1 as a critical molecule that regulates multiple aspects of cancer cells and maintains all major cancer hallmarks." (PMID 41714589, 2026). "PLK1 has emerged as a key regulator of multiple transcription factors, including STAT3, c-Myc, FOXM1, and β-catenin, positioning it as a promising combinatorial therapeutic target for disrupting oncogenic signaling networks in cancer." (PMID 41539998, 2026). "We also discuss the opportunity and challenges for therapeutically targeting FOXM1 to induce apoptosis in drug-resistant cancers." (PMID 41714589, 2026). "The forkhead box M1 (FOXM1) transcription factor serves as a master regulator of oncogenic signaling networks that drive cancer progression." (PMID 41943830, 2026). "FOXM1, which is upregulated in multiple tumors, plays a key role in promoting cancer cell proliferation." (PMID 41413918, 2025). "As an important proliferation-related transcription factor, FOXM1 is highly expressed in most cancers and plays an important role in cell cycle and cell growth." (PMID 40566633, 2025). "FOXM1 is therefore upregulated in a pan-cancer range, across all TCGA datasets with a corresponding normal tissue in GTEx." (PMID 39858603, 2025). "The overexpression of FOXM1 has consistently been documented across various cancer types, including lung, breast, prostate, liver, and pancreatic cancers, as well as melanoma." (PMID 39781349, 2025). "Drug therapies targeting FOXM1 have shown promise in slowing cancer progression and inducing apoptosis." (PMID 40002266, 2025). "As a master regulator of G1/S and G2/M cell cycle transitions, FOXM1 promotes cancer progression mainly by accelerating cell cycle and proliferation." (PMID 40003882, 2025). "Reactivation of FOXO3A or suppression of FOXM1 in cancer cells reduces DNA repair capacity and cell survival rates while augmenting cell death and enhancing the efficacy of DNA-damaging anticancer therapies." (PMID 40699718, 2025). "This analysis revealed a significant enrichment of E2F4 and FOXM1 targets in evolved cancer cell lines and in aneuploid tumors." (PMID 39930267, 2025). "As FOXM1 is also a key component of cell division and replication, its overexpression is observed in many cancer types." (PMID 40149290, 2025). "Thiostrepton selectively downregulates FOXM1 mRNA expression and activity, resulting in senescence and apoptosis of several types of cancer cells." (PMID 40820379, 2025). "CCT4 expression was positively correlated with oncogenic proteins involved in cell proliferation and survival, including PCNA, Cyclin B1, FOXM1, across multiple cancer types." (PMID 41403933, 2025). "The second limitation is that FOXM1, like all human genes hijacked by cancer, also possesses a physiological pro-proliferative function, and it is also active in non-cancer cells." (PMID 39858603, 2025). "These compounds that inhibit FOXM1 expression have demonstrated anti-tumor effects, with some also enhancing cancer cell sensitivity to drugs." (PMID 40612352, 2025).
cancer (continued). "FOXM1 is a key molecule that promotes epithelial-mesenchymal transition of tumor cells, and inhibition of its expression can effectively prevent cancer cell metastasis." (PMID 39781349, 2025). "The pan-cancer upregulation of FOXM1 reverberates in its target genes, as highlighted by Master Regulator Analysis across the 15 selected cancer types." (PMID 39858603, 2025). "Strikingly, the consensus targets of transcription factors E2F4 and FOXM1 were strongly enriched in our in vitro evolution model, as well as in aneuploid cancers." (PMID 39930267, 2025). "The anti-cancer properties of thiostrepton are primarily ascribed to the inhibition of the oncogenic transcription factor FOXM1." (PMID 40867592, 2025). "For example, FOXM1 is a major oncogene in various cancers such as colorectal, breast, and lung cancer, and is known to contribute to tumour metastasis and treatment resistance." (PMID 39777582, 2025). "FOXM1 plays a pivotal role in cancer progression, including BC, by promoting unhindered proliferation, tumorigenesis, cell migration, epithelial–mesenchymal transition (EMT), and metastasis." (PMID 40002266, 2025). "Recent attention has focused on FOXM1 due to its significant overexpression in various human cancers and its crucial role in tumor advancement." (PMID 40612352, 2025). "The outcomes of the IHC staining exhibited that the pattern of UBE2S expression was evident, namely, in the cytoplasm and nucleus, HIF‐1α and FOXM1 expression were major situated in the cancer cells nucleus." (PMID 41427004, 2025). "While our study focused on established cell lines, future research should explore FOXM1 dynamics in patient‐derived cancer models to elucidate clinical implications." (PMID 40091487, 2025). "Regarding cancer antigens, our findings highlight the expression of FOXM1 and SPARC as being significantly lower in liver metastases than in primary CRC." (PMID 40806530, 2025). "Forkhead box M1 (FOXM1), a proliferation-associated transcription factor, is highly expressed in various cancers." (PMID 40548063, 2025). "One possible mechanism can be the release of inflammatory cytokines by the cancer cells after FOXM1 inhibition as observed in our RNA-seq data." (PMID 40630538, 2025). "FOXM1 is a Forkhead family transcription factor that is well known to promote all the hallmarks of cancer." (PMID 39880086, 2025). "GTSE1, which is highly expressed in various cancers, including PCa, and linked to poor prognoses, promotes PCa cell proliferation by activating the SP1/FOXM1 signaling pathway." (PMID 40626556, 2025). "A cancer-wide meta-analysis identified the FOXM1-regulatory network as a major predictor of adverse outcomes." (PMID 39880086, 2025). "Inhibition of FOXM1 activity holds promise for effectively suppressing tumor cell proliferation and metastasis, emerging as a novel strategy for cancer treatment." (PMID 39781349, 2025). "The critical role of FOXM1 in tumor development and cell biology has made it a prominent focus of cancer research." (PMID 39781349, 2025). "Its pro-apoptotic effects are likely mediated through activation of FOXO3a, which in turn inhibits FOXM1 expression, thereby reducing cancer cell proliferation and survival." (PMID 40746724, 2025). "We have previously demonstrated that FOXM1 knockdown (KD) induces sensitivity to cytotoxic or BCL2-targeted therapy in several human cancers, including AML." (PMID 39880086, 2025).
cancer (continued). "Given these properties, developing pharmacological solutions to inhibit FOXM1 would seem like the perfect strategy to combat or mitigate tumor progression across all cancer types." (PMID 39858603, 2025). "Predicted matching epitopes included various cancer antigens, including FOXM1 (IYTWIEDHF), mucin 1 (LLLLTVLTV), Cancer/testis antigen 1 (AMPFATPMEA, GAARASGPGGGAPRG) and ADAM10 (GQYGNPLNK)." (PMID 40211048, 2025). "We observed a significant and consistent upregulation of FOXM1 in cancer cells, when compared to normal cells, across all three tumor microenvironments (p = 1.4 × 10−76 for BrCA, p = 1.0 ×10−92 for LuCA and p < 2.2 × 10−308 for CRCA." (PMID 39858603, 2025). "This overexpression is associated with poor clinical outcomes for patients, highlighting FOXM1’s role as a potential therapeutic target in cancer treatment." (PMID 41465190, 2025). "FOXM1 inhibitors are currently being elucidated that promote chemosensitivity in a wide range of cancers." (PMID 40517236, 2025). "A recent study has demonstrated that FOXM1 inhibitors can sensitive human cancer cells to various cancer therapies, further highlighting the tumour-promoting role of FOXM1." (PMID 39736850, 2025). "FoxM1 is an important transcription factor in cancer stem cells, playing a significant role in various cancers." (PMID 40050970, 2025). "FOXM1 is highly upregulated in BC, promoting tumorigenesis, cancer growth, and progression, and phosphorylation regulates FOXM1 subcellular distribution, PPIs, and partners of gene regulation." (PMID 39860065, 2025). "More importantly, it is now evident that the downregulation of FoxM1 mediated by Thio induces apoptotic cell death in various cancer cell lines, such as MCF7 breast carcinoma cells, lung cancer, melanoma, and colorectal cancer." (PMID 40628925, 2025). "This filtering step was essential to minimize background noise and enable precise comparisons of FOXM1 expression levels across cancer and normal tissues." (PMID 39858603, 2025). "FOXM1 is upregulated during early cancer development and exerts multiple tumor-promoting activities through stimulation of cell cycle progression and suppression of senescence." (PMID 39930267, 2025). "The upregulation of FOXM1 enhances the proliferation, migration, and invasive potential of cancer cells." (PMID 40612352, 2025). "The regulation of downstream target gene expression by FOXM1 promotes cancer cell proliferation and metastatic implantation via multiple pathways, further highlighting its critical role in OC development." (PMID 40612352, 2025). "The higher the cancer stage, the higher the expression level of FOXM1, and the poorer the prognosis." (PMID 40612352, 2025). "Despite its role in cancer being acknowledged in literature, FOXM1 is altered in only 3% of all human cancer genomes (collected in the TCGA Pan-Cancer Atlas), with amplifications being the most common event, followed by somatic point mutations." (PMID 39858603, 2025). "Downstream target genes of FOXM1 have been identified that affect cancer cell invasion and migration." (PMID 40612352, 2025). "FOXM1 from exosomes derived from TNBC can promote cancer progression by activating IDO1 transcription in macrophages to inhibit ferroptosis and induce M2 polarization in tumor-associated macrophages." (PMID 40657248, 2025). "Thiostrepton has been reported to have an anti-cancer effect on various cancer cell lines by blocking the transcriptional activity of FoxM1 and reducing its expression, leading to apoptosis induction." (PMID 40628925, 2025). "Studies have found that FOXM1-mediated inactivation of inflammasome transcription can promote the immunosuppressive microenvironment of CC and accelerate the immune escape of cancer cells." (PMID 40589640, 2025). "The direct effect of thiopeptides on cancer cell growth and Foxm1 expression was evaluated using thiostrepton, the thiopeptide produced by Streptomyces spp., as C. acnes thiopeptide is not commercially available." (PMID 38014984, 2024).
cancer (continued). "Forkhead-box M1 (FOXM1) is a proliferation-associated transcription factor, overexpressed in almost all the cancers, making its regulation worth investigating." (PMID 39272919, 2024). "This process is also regulated via FOXM1 in the same way as other cancer-related genes, including TYMS, another major protagonist in our screen that was found to be vital to metastatic cells." (PMID 39518122, 2024). "Although the decrease in expression of FOXA1 and FOXK2 were less dramatic than FOXM1, it is likely that these effects are biologically significant, and in part account for the anti-cancer activity of NB compounds." (PMID 38704607, 2024). "Mechanically, FoxM1 is a transcriptional factor that plays important roles in the progression and development of various cancers, including NPC." (PMID 38698443, 2024). "FOXM1 promotes cell cycle progression and cancer cell proliferation, tumor growth and metastasis, and high levels of FOXM1 are associated with poor patient survival." (PMID 38980505, 2024). "MALAT-1 competitively binds to miR-125a-3p and activates FoxM1, inducing cancer proliferation and invasion." (PMID 38201661, 2024). "Previous studies have reported that FOXM1 is overexpressed in various cancers and sarcomas including breast cancer, melanoma, angiosarcoma, lung cancer, pancreatic cancer, gastric cancer, prostate cancer, leukemia, leiomyosarcoma, and synovial sarcoma 48–59." (PMID 38374400, 2024). "Taken together, this data shows a very high probability of FOXM1 being the main mediator of STL001 effects on gene expression program in cancer cells." (PMID 38697979, 2024). "Previously, we reported that PVT1 epigenetically maintains FOXM1 protein level, which is protein characterized by its role in inducing sensitization to antitumor drugs in cancer cells." (PMID 38098223, 2024). "In BRCA, FOXA1 and FOXM1 mRNA were higher in cancer tissues than in precancerous tissues (P < .001, the difference was statistically significant)." (PMID 38608123, 2024). "It suggests that the sensitization effect of STL001 in different cancer cells is conveyed specifically through FOXM1 suppression." (PMID 38697979, 2024). "In conclusion, FOXM1 inhibitors synergize with different traditional and targeted anti-cancer therapies." (PMID 38398147, 2024). "There is in fact growing enthusiasm for targeting FOXM1 in cancer using newly developed FOXM1 inhibitors, particularly for controlling drug resistance as part of combination therapies." (PMID 39347707, 2024). "Given the multifaceted functions in cancer progression, targeting FOXM1 has emerged as a promising therapeutic approach." (PMID 38918225, 2024). "Although chronic SPDEF and FOXM1 can promote or inhibit cancer, cyclic FOXM1 activation has recently been shown to increase the lifespan of mice." (PMID 37644339, 2024). "While cancer cells are markedly suppressed by FOXM1 inhibitor treatment, with continued long-term NB compound treatment, there is pressure to develop resistance." (PMID 38980505, 2024). "STL427944 was found to block FOXM1 activity by inducing the relocalization of nuclear FOXM1 to the cytoplasm and promoting its autophagic degradation, it sensitizes various cancer cells to multiple traditionally used chemotherapies at very high concentrations." (PMID 38697979, 2024). "This review explores the role of FOXM1 in cancer progression and highlights the current status of efforts to develop effective FOXM1 inhibitors." (PMID 39594778, 2024). "FOXM1, a member of the forkhead box protein family, is a crucial transcription factor that regulates multiple activities of cancer cells, such as growth, metastasis, recurrence, and stem cell features." (PMID 39086352, 2024). "FOXM1 has been found to be overexpressed in cancer cells that are resistant to drugs that damage their DNA, and its expression can block the effectiveness of genotoxic agents." (PMID 37976368, 2024).
cancer (continued). "The sensitization of chemoresistant cancer cells to chemotherapies, especially to DNA-damaging agents, is the well-known effect of FOXM1 inhibition in cancer cells." (PMID 38697979, 2024). "This has made FOXM1 a crucial factor in the occurrence and progression of cancer as a group of diseases that arises from dysregulation in a cell cycle." (PMID 39272919, 2024). "The STL427944 reduces the chemoresistance of cancer cells by inducing FOXM1 degradation and is confirmed in various cancer cell lines as a selective inhibitor of the FOXM1 pathway at very high concentrations." (PMID 38697979, 2024). "Thiostrepton inhibits the transcriptional activity of FOXM1 and its expression through the inhibition of proteasomal activity in cancer cells." (PMID 39594778, 2024). "Its interaction with transcription factors like Forkhead Box M1 (FOXM1) and influences from the tumor microenvironment have been documented, affecting its activity in cancer cells." (PMID 39272816, 2024). "FOXM1 can thereby promote cancer cell proliferation and chemotherapy resistance by facilitating cell cycle progression." (PMID 39086352, 2024). "Understanding these pathways provides valuable insights into potential therapeutic strategies for targeting FOXM1 in cancer treatment." (PMID 39594778, 2024). "FOXM1-dependent fatty acid oxidation-mediated ROS modulation is a cell-intrinsic drug resistance mechanism in cancer stem cells." (PMID 39607749, 2024). "FoxM1 is a transcription factor that increases cancer progression by inducing migration, invasion, metastasis, and EMT in cancer cells." (PMID 38201661, 2024). "Small-molecule FOXM1 inhibitors are promising compounds whose therapeutic benefits can be applied to different pediatric and adult cancers." (PMID 38398147, 2024). "In the last few years, a variety of pharmacological inhibitors of FOXM1 in cancer have been developed." (PMID 39086352, 2024). "FOXM1 plays a central role in cancer initiation, and the upregulation of FOXM1 expression is considered to be an early event in cancer development." (PMID 37976368, 2024). "Abnormally high expression of FOXM1 in cancers compared to normal tissue makes FOXM1 an attractive target for pharmacological inhibition." (PMID 38398147, 2024). "It is noteworthy that PID_AURORA_B_Pathway which is involved in the proliferation of cancer cells by positive regulation of cell cycle and G2/M phase transition also represents the activity of direct FOXM1 downstream effectors." (PMID 38697979, 2024). "FOXM1 plays a crucial role in cancer progression, influencing various steps such as epithelial–mesenchymal transition (EMT), cell proliferation, migration and premetastatic niche formation." (PMID 38063438, 2024). "ETV4 and FOXM1 are the two common overregulated TFs in the three types of cancer and are important in the regulation of other key TFs and DEGs, as well as the formation of co-regulatory complexes, during the tumorigenic process in the gut-lung axis." (PMID 39228892, 2024). "In the cancer scenario, it has been demonstrated that FOXM1 induces tumor proliferation, migration, invasion, and angiogenesis, which are processes shared by trophoblast cells during the peri-implantation phase." (PMID 38338955, 2024). "Among the candidates, FOXM1 emerged as a promising target due to its pivotal role in regulating tumorigenesis and cancer progression, as supported by previous studies." (PMID 38063438, 2024). "A study has shown that Metformin dramatically reduced FOXM1 protein levels by reducing FOXM1 expression in cancer cells, which resulted in faster apoptosis and cell cycle arrest at the G0/G1 and G2/M phases, both of which reduced cell proliferation." (PMID 38922530, 2024). "Because of its high expression and crucial roles in tumorigenesis, FOXM1 has been determined to be a cancer therapeutic target." (PMID 39060421, 2024). "For example, the widely used FOXM1 inhibitor Siomycin A can restore chemotherapeutic sensitivity in a variety of cancer cells." (PMID 39086352, 2024).